MELK (maternal embryonic leucine zipper kinase)
Diseases named in the same sentence as MELK in open-access papers (continued):
Sharing a sentence is not in itself a finding about the gene and the disease.
cancer (continued). "The implication of MELK in tumor growth makes it an attractive therapeutic target for cancer therapy." (PMID 31740676, 2019). "Targeting MELK in different cancer cell types, using either siRNA knockdown or pharmacological inhibition, resulted in an impaired tumor growth by inducing apoptosis and/or decreasing cell proliferation both in vitro and in vivo." (PMID 31740676, 2019). "In agreement with our data, high levels of MELK have been previously shown to directly correlate with an unfavorable outcome in various cancer entities." (PMID 31861475, 2019). "MELK has been shown to be differentially expressed in cancer stem cells or tumor-initiating cells, which drives cell cycle progression and tumor formation." (PMID 31358735, 2019). "Yet, MELK is up-regulated in many cancer types, and high levels of MELK expression have been reported to confer a dismal clinical prognosis." (PMID 29417930, 2018). "MELK has been reported to support cancer cell proliferation by phosphorylating various proteins involved in splicing, translation, metabolism, and cell cycle progression." (PMID 29417930, 2018). "Despite the conflicting in vitro data, MELK expression remains one of the strongest predictors of patient mortality in diverse cancer types." (PMID 29417930, 2018). "To assess MELK function in cancer, we used CRISPR/Cas9 to generate mutations in MELK in four different cancer cell lines." (PMID 29417930, 2018). "Several transcription factors, such as oncoprotein FoxM1 and c-JUN, have been reported to promote MELK in cancer cells." (PMID 29416794, 2018). "Additional, potentially cancer‐relevant pathways that were affected by both MELK knock‐down and OTS167 treatment included apoptosis, cytoskeletal rearrangement and DNA damage repair pathways." (PMID 29437778, 2018). "The three recent eLife articles certainly call into question many of the previous reports regarding MELK dependency in cancer cells." (PMID 29417929, 2018). "More than 30 published articles have suggested that a protein kinase called MELK is an attractive therapeutic target in human cancer, but three recent reports describe compelling evidence that it is not." (PMID 29417929, 2018). "To examine the link between MELK and cell division in cancer, we compared the levels of MELK expression with five well-characterized proliferation markers: MKI67, PCNA, CCNB1, MCM2, and TOP2A." (PMID 29417930, 2018). "Maternal embryonic leucine zipper kinase (MELK) is a serine/threonine kinase overexpressed in various organ-specific stem cells and cancers." (PMID 29416794, 2018). "In total, these results suggest that the observed pattern of MELK expression in cancer can be explained by the fact that MELK is up-regulated in mitotic cells." (PMID 29417930, 2018). "The molecular mechanism regulating MELK overexpression in cancer cells and the role of MELK in NB tumorigenesis remains ambiguous." (PMID 29416794, 2018). "Upregulation of MELK drives cell cycle progression and tumor formation and it has been shown to be differentially expressed in cancer stem cells or tumor-initiating cells." (PMID 29783958, 2018). "Columns 2–5 indicate which articles reported certain kinds of evidence to make the link between MELK and cancer, column 6 indicates the studies that used a MELK inhibitor called OTS167 (which is currently undergoing clinical trials)." (PMID 29417929, 2018). "In total, these results demonstrate that MELK is dispensable for the proliferation of cancer cells in vitro and in vivo." (PMID 29417930, 2018). "While we stand by our original conclusion regarding the role of MELK in cancer cell proliferation, we recognize that these more recent findings raise important questions regarding the merits of MELK as a target for cancer drug development." (PMID 29528283, 2018).
cancer (continued). "The high expression rates of MELK were 80% (12/15) in cancer metastatic patients and 30% (3/10) in metastasis‐free patients, respectively (P = 0.034)." (PMID 30334367, 2018). "Analysis of gene expression data from cohorts of cancer patients identifies MELK expression as a correlate of tumor mitotic activity, explaining its association with poor clinical prognosis." (PMID 29417930, 2018). "The Maternal Embryonic Leucine Zipper Kinase (MELK) has been identified as a promising therapeutic target in multiple cancer types." (PMID 29417930, 2018). "Initial interest in blocking MELK function in cancer stemmed from the discovery that it was over-expressed across cancer types." (PMID 29417930, 2018). "In total, these results cast doubt on the possibility that MELK-specific inhibition will serve as a useful monotherapy in cancer." (PMID 29417930, 2018). "In aggregate, these published studies would seem to make a compelling case for a likely role for MELK in a variety of human cancers." (PMID 29417929, 2018). "In total, our results demonstrate the power of CRISPR/Cas9-based genetic approaches to investigate cancer drug targets, and call into question the rationale for treating patients with anti-MELK monotherapies." (PMID 29417930, 2018). "A number of publications support the notion that MELK is a key regulator of progression and potential therapeutic target in multiple cancer types." (PMID 29437778, 2018). "The 33 articles listed in column 1 of this table suggest that MELK has a role in a variety of human cancers, which makes in a candidate therapeutic target for cancer drugs." (PMID 29417929, 2018). "As a mitotic kinase highly expressed in many cancer types, MELK has been identified as a promising target for therapeutic intervention." (PMID 28337968, 2017). "To extend these observations, we repeated the GFP dropout experiments in six Cas9-expressing cell lines (A375, Cama1, HCT116, NCI-H1299, T24, and U118-MG) from other cancer types previously suggested to require MELK expression." (PMID 28337968, 2017). "Over a dozen previous publications have reported that MELK is a cancer dependency, as blocking MELK with RNAi or small molecules inhibited the proliferation of cell lines derived from multiple tumor types." (PMID 28337968, 2017). "We performed a total of 91 competition assays (7 MELK gRNAs in 13 different cell lines) that failed to reveal an effect of MELK loss on cell fitness, further strengthening our conclusion that MELK is dispensable for cancer cell proliferation." (PMID 28337968, 2017). "MELK is overexpressed in various types of solid and hematological cancers, and has been reported to correlate with poor prognosis of cancer patients." (PMID 28938528, 2017). "In the past decade, multiple studies have reported overexpression of MELK in various cancers, including breast, brain, colorectal, lung and ovarian." (PMID 28926338, 2017). "The Maternal Embryonic Leucine Zipper Kinase (MELK) has been reported to be a genetic dependency in several cancer types." (PMID 28337968, 2017). "Previous research utilizing RNA interference to knock down MELK has indicated that MELK expression is required for cancer cell proliferation." (PMID 28337968, 2017). "Some of these pan-cancer genes have previously been demonstrated to be driver genes, oncogenes, or even candidate therapeutic targets, such as MELK." (PMID 28489584, 2017). "A competitive type I kinase inhibitor, OTSSP167 (OTS167) has been designed to inhibit MELK activity, and its efficacy has been explored in several cancers including in TNBC cell lines." (PMID 28235006, 2017). "Synthetic lethal screens and further in vivo investigation will shed light on MELK’s function in development and cancer." (PMID 28337968, 2017).
cancer (continued). "One possibility, not ruled out by our studies, is that OTS167 exhibits polypharmacology, and kills cancer cells by inhibiting multiple kinases, potentially including MELK." (PMID 28337968, 2017). "The MDA-MB-231and Cal51 MELK-KO clones exhibited robust proliferation, demonstrating that MELK is fully dispensable for the growth of these cancer cell lines." (PMID 28337968, 2017). "The Maternal Embryonic Leucine Zipper Kinase (MELK) has received substantial attention as a potential cancer cell addiction and promising target for drug development." (PMID 28337968, 2017). "MELK likely has complex functions in cells including embryonic development, maintenance of progenitor cell fate, cell cycle regulation, and potentially cancer development." (PMID 28926338, 2017). "Since MELK was considered as an ideal therapeutic target for cancer treatments, we developed potent MELK inhibitors." (PMID 28938528, 2017). "MELK expression is upregulated in mammary stem cells and in undifferentiated cancers, where it correlates with poor prognosis and potentially mediates treatment resistance." (PMID 28235006, 2017). "The average expression level of MELK in 53 SCLC cell lines was high as being ranked to the 5th of 33 different cancer types." (PMID 26871945, 2016). "Since targeting MELK alone or with other treatment modalities has a possibility to overcome therapeutic resistance by suppressing CSCs as well as cancer proliferation, many efforts have been paid to develop a MELK kinase inhibitor(s)." (PMID 26918358, 2016). "Elevated MELK expression was reported in various types of human cancer including hematological malignancies with hardly detectable expression in normal organs except the testis." (PMID 26918358, 2016). "Through the analysis of MELK itself and these molecules, MELK was shown to be involved in many aspects of cancer traits, such as cell proliferation, anti-apoptosis and cell invasion." (PMID 26918358, 2016). "In conclusion, we have elucidated that MELK plays pivotal roles in cancer progression and/or stem cell maintenance in SCLC cells." (PMID 26871945, 2016). "MELK is currently regarded as a promising target for novel cancer therapy, and several MELK small molecule inhibitors including OTSSP167 have been published." (PMID 27082996, 2016). "We assume that since MELK is highly expressed in stem cells and cancer cells are considered to originate from stem cells, cancer tissues including a relatively high proportion of cancer stem cells reveal higher MELK expression." (PMID 26918358, 2016). "It is also suggested that MELK is involved in the maintenance of cancer stem cells (CSCs), which possess higher tumorigenicity and are, in general, resistant to conventional anti-cancer therapies." (PMID 26871945, 2016). "MELK has been considered a potential target for cancer therapy because of the interaction with multiple proteins at distinct stages of tumorigenesis, and the first MELK-specific small molecular compound, OTSSP167, was developed." (PMID 26973435, 2016). "It has been reported that MELK is frequently and highly upregulated in various types of human cancer, both solid tumors and hematological cancers, and that elevated MELK expression is correlated with poor prognosis of cancer patients." (PMID 26871945, 2016). "T–lymphokine-activated killer cell–originated protein kinase (TOPK) and maternal embryonic leucine zipper kinase (MELK) have been reported to play critical roles in cancer cell proliferation and maintenance of stemness." (PMID 26933922, 2016). "We demonstrate that OTS167-treated cancer cells or tumor tissues reduce MELK protein levels and a proliferation marker Ki67." (PMID 26918358, 2016).
cancer (continued). "MELK expression was positively correlated with lymph node involvement, distant metastasis, and more advanced cancer stages." (PMID 26701722, 2016). "In fact, we demonstrated that dual blockade with low doses of TOPK inhibitor (OTS514) and MELK inhibitor (OTS167) achieved the additive cancer cell killing effects rather compared with the single treatment." (PMID 26933922, 2016). "These morphological changes were also observed in other MELK-overexpressing cancer cells when they were treated with 20 nM of OTS167 for 24 hours." (PMID 26918358, 2016). "We previously reported MELK (maternal embryonic leucine zipper kinase) as a potential and promising molecular target for development of novel cancer therapy." (PMID 26918358, 2016). "MELK has become an attractive target for novel anti-cancer therapy due to its characteristic overexpression in cancer cells and cancer stem cells." (PMID 27082996, 2016). "For example, MELK expression is restricted to proliferating cells in early embryonic development, and is expressed at particularly high levels in cancer cells." (PMID 25852826, 2015). "Because the inhibition of MELK has a greater effect on cancer stem cells than normal stem cells, the development of novel pharmaceutical therapies that target MELK is an active area of clinical investigation." (PMID 25852826, 2015). "In light of these preclinical studies, novel therapeutics have been developed to selectively target MELK in cancers." (PMID 25852826, 2015). "Preferential upregulation of MELK in cancers and recent data from knockdown and forced overexpression studies suggest that MELK promotes cancer cell growth." (PMID 25852826, 2015). "As demonstrated by Compound 1 (C1) and OTSSP167, discoveries of novel Small Molecule Drugs (SMDs) that inhibit MELK can be potential therapies for cancers with high levels of MELK expression." (PMID 25852826, 2015). "MELK overexpression has been identified in several human cancers: prostate, breast, brain, colorectal and gastric." (PMID 25852826, 2015). "MELK is a protein kinase and candidate oncoprotein, which is dysregulated in several types of cancer, as well as being involved in resistance to apoptosis." (PMID 26096802, 2015). "In cancer cells, MELK forms a protein complex with the transcription factor/oncogene FOXM1, a master regulator for cell cycle progression." (PMID 25852826, 2015). "MELK knockdown by small interfering RNA (siRNA) or short hairpin RNA (shRNA) induced apoptosis of cancer stem cells in GBM stem cells (GSCs) both in vitro and in vivo." (PMID 25852826, 2015). "Maternal embryonic leucine zipper kinase (MELK) is a serine/threonine kinase that is highly expressed in various organ-specific stem cells and cancers." (PMID 24739874, 2014). "MELK is overexpressed in many cancer cell types, but it has been studied primarily as a regulator of cellular proliferation, not in migration." (PMID 25194022, 2014). "Maternal embryonic leucine-zipper kinase (MELK), which was reported to be frequently up-regulated in various types of solid cancer, plays critical roles in formation and maintenance of cancer stem cells." (PMID 25365263, 2014). "Unlike other mitotic factors like Aurora A, Aurora B, and PLK1, that are normally essential, MELK presents a unique mitotic kinase that is only required by a subset of cancer cells, and is therefore an excellent therapeutic target." (PMID 24844244, 2014). "MELK is considered to be a promising drug target for anticancer therapy because overexpression and hyperactivation of MELK is correlated with several human cancers." (PMID 24531485, 2014). "Remarkably, down-regulation of MELK led to a substantial regression of tumors arising from BBC cells but had little effect on tumors derived from luminal cancer cells." (PMID 24844244, 2014). "Prior studies have suggested that both FOXM1 and MELK play essential roles in cell cycle progression, cancer cell growth, and maintenance of stem cell state of GBM." (PMID 23404835, 2013).
cancer (continued). "MELK is aberrantly reactivated in cancer stem cells, thereby providing a growth advantage for neoplastic cells and derived tumor progression." (PMID 24185907, 2013). "Prior studies have suggested that both FOXM1 and MELK play essential roles in the cell cycle progression, cancer cell growth, and maintenance of stem cell state of GBM." (PMID 23404835, 2013). "DLG7 and MELK were up-regulated in cancers compared to normal endometrial specimens and more highly in serous cancer as compared to endometrioid cancer." (PMID 23785665, 2013). "The identification of up-regulated MELK has the potential to be exploited clinically if a tumor growth phenotype is attributed to MELK, as kinases have often been effectively targeted by small molecule therapy in cancer." (PMID 23785665, 2013). "Recently MELK has been described as over-expressed in carcinomas and in particular their stem cell niche." (PMID 23785665, 2013). "In summary, we have demonstrated that MELK plays crucial roles in cancer progression and/or stem cell maintenance through phosphorylation of its substrate proteins." (PMID 23283305, 2012). "In vitro anti-proliferative assay using A549 (lung), T47D (breast), DU4475 (breast), and 22Rv1 (prostate) cancer cells, in which MELK was highly expressed, revealed IC50 values of 6.7, 4.3, 2.3, and 6.0 nM, respectively." (PMID 23283305, 2012). "Taken together, these results suggest that OTSSP167 suppressed mammosphere formation of cancer stem cells through the reduction of phosphorylated PSMA1 by inhibition of the MELK activity." (PMID 23283305, 2012). "Currently, MELK has been predominantly studied in the context of tumorigenesis and cancer therapy." (PMID 40539108, 2025). "Furthermore, its minimal expression in normal tissues makes MELK an attractive target for cancer-specific interventions." (PMID 40076867, 2025). "Furthermore, RNA interference-mediated MELK knockdown has confirmed that MELK expression is vital for cancer cell proliferation and survival." (PMID 39871325, 2025). "In cancer, MELK is involved in regulating cell cycle progression, apoptosis, and proliferation." (PMID 40076867, 2025). "In addition, MELK has been shown in multiple cancers to activate PI3K–Akt–mTOR signaling, and these mitogenic pathways can indirectly promote YAP/TAZ activity." (PMID 41278210, 2025). "Given its central role in driving abnormal cell proliferation and migration in cancer, MELK may have broader relevance in proliferative vascular diseases." (PMID 41278210, 2025). "MELK knockdown reduced cancer cell proliferation and migration." (PMID 40709174, 2025). "MELK overexpression has been described in many cancers and cancer stem cells." (PMID 39355119, 2024). "Interestingly, evidence indicates that MELK also functions in regulating the radioresistance of glioma and interfering with DNA damage tolerance in proliferating cancer cells." (PMID 38970074, 2024). "MELK is explored as a potential therapeutic target for cancer." (PMID 38382096, 2024). "Targeting MELK seems a good choice for developing novel cancer therapy." (PMID 39355119, 2024). "Intriguingly, MELK is an attractive therapeutic target for the modulation of cancers." (PMID 38652219, 2024). "Even though the molecular function is still unknown, MELK is known to be overexpressed in multiple cancers, including melanoma, breast cancer, and renal cell carcinoma." (PMID 36674843, 2023). "The involvement of MELK in many human cancers, including HCC, has been documented." (PMID 35511171, 2022). "The prognosis of MELK in various cancers was analyzed in GEPIA." (PMID 35693941, 2022). "MELK has been shown to activate mitotic regulatory genes by activating FOXM1 in other cancers." (PMID 36151566, 2022). "We used different methods to investigate the prognostic effect of MELK in the 14 types of cancer." (PMID 35693941, 2022).